TK1 (thymidine kinase 1)
Diseases named in the same sentence as TK1 in open-access papers (continued):
Sharing a sentence is not in itself a finding about the gene and the disease.
tumor (continued). "While CA199 and 8-oxo-dG correlated with one another, TK1 did not correlate with 8-oxo-dG, indicating that 8-oxo-dG in serum may not correlate with tumour proliferation rate, but instead with the presence of tumour in the body." (PMID 29951164, 2018). "Therefore, TK1 activity modifications during chemotherapy may not accurately reflect changes in the proliferation status of the tumor." (PMID 29662653, 2018). "Although TK1 expression has been detected in OSCC tissue specimens, its functional role in regulating tumor invasion and metastasis has not been fully elucidated." (PMID 40564887, 2025). "Using RNA-sequencing data from The Cancer Genome Atlas, we observed a significantly higher expression of TYMS, TK-1, and SLC29A1 in tumor tissue (n = 371) than in adjacent nonmalignant tissue (n = 50; P < 0.05)." (PMID 32513905, 2020). "Based on the findings from TIMER, we proposed that LMNB1, TK1, ZWINT, and RACGAP1 are mainly expressed in PCa cells rather than immune cells, and their functions do not relate to immunological regulation of the tumor microenvironment." (PMID 31306099, 2019). "However, results of our study indicate that Tk1, the substrate of [18F]FLT, is present also in immune cells and not uniformly distributed in tumor." (PMID 40520013, 2025). "The intensity of TK1 expression increased significantly from CIN I to CIN III and from CIN III to the invasive cervical carcinoma pathological stage II/FIGO stage IA + IIA, but did not increase further in the advanced tumor stages." (PMID 23693054, 2013). "Although TK1 is not a specific proliferation marker, TK1 is regulated within the cell cycle, and the 18F-FLT uptake level within tumors usually reflects the fraction of tumor cells in the S-phase, in which the TK1 expression level is the highest." (PMID 24191959, 2013).
cancer (131 papers, 2009 to 2026). A tumor composed of atypical neoplastic, often pleomorphic cells that invade other tissues. "PGRMC1 exhibited a significant correlation with TK1 when all cancers were combined, although the magnitude of these associations was weak (r = 0.154; P = 9 × 10−08)." (PMID 39804138, 2025). "More recently, it has been shown that high expression of TK1 is significantly associated with immune suppression during cancer development." (PMID 40942076, 2025). "PGRMC1 exhibits a significant correlation with TK1 when all cancers are combined, although the magnitude of these associations is weak." (PMID 39804138, 2025). "Thymidine kinase 1 (TK1) is recognized as a cell proliferation biomarker that has potential value in cancer risk assessment." (PMID 40717135, 2025). "Herein, we developed a machine learning (ML) model, i.e., Alertix-Cancer Risk Index (Alertix-CRI) which incorporates canine TK1 protein, CRP levels in conjunction with an age factor." (PMID 40351765, 2025). "•Thymidine kinase 1 (TK1) serves as a significant biomarker for cell proliferation and cancer progression, with elevated levels associated with higher metastasis level." (PMID 39006942, 2024). "TK1 participates in cell proliferation and plays a potential role as a diagnostic tool and prognostic factor in evaluating cancer treatment and progression." (PMID 38761234, 2024). "The role of cellular TK1 as a potential biomarker has been previously evaluated in breast and other cancer types, mostly associated with worse prognosis." (PMID 38175448, 2024). "The ECL-dot blot assay is highly sensitive, detecting as little as 0.01 pmol/L STK1p, which is approximately 120 times more sensitive than a TK1 enzyme-linked immunosorbent assay, which can detect invisible malignant tumors." (PMID 38887267, 2024). "Another survey with 35,365 participants also showed that the concentration of TK1 protein in the serum is a reliable indicator of early cancer progression risk." (PMID 36831773, 2023). "The relationship between TK1 and the Hallmark pathway in the TCGA pan-cancer cohort was then analyzed." (PMID 37767092, 2023). "TK1 is universally recognized as a hallmark of cellular proliferation and elicits oncogenic effects in diverse malignant neoplasms." (PMID 37767092, 2023). "Pan-cancer analysis also demonstrated that TK1 is associated with poor prognosis and activation of proliferation pathways in multiple cancers." (PMID 37767092, 2023). "Our investigation elucidated the interrelationship between TK1 and cell cycle-associated cascades, as well as proliferation-linked pathways across a spectrum of cancer types." (PMID 37767092, 2023). "Increased levels of TK1 in both tumors and serum are associated with disease stage and, as cancer progresses, serum TK1 levels increase with disease stage." (PMID 35239730, 2022). "In veterinary medicine, canine serum TK1 activity has also been shown to be a useful diagnostic and prognostic biomarker for hematological malignancies and it can be used to monitor cancer treatment." (PMID 34579716, 2021). "The upregulation of a number of rate-limiting enzymes in pyrimidine biosynthesis such as deoxythymidylate kinase (DTYMK), thymidylate synthase (TYMS), and thymidine kinase 1 (TK1) in HCC is associated with cancer stemness and poor prognosis." (PMID 33747521, 2021). "Recent findings indicate that, beyond its role as a cancer cell proliferation biomarker, intracellular TK1 is linked to cancer cell invasion and progression." (PMID 33292474, 2020). "Recently, the expression of membrane associated TK1 forms in both cancer cell lines and clinical samples has been reported." (PMID 32317865, 2020). "During flow cytometry experiments we found that several of the anti TK1 antibodies were able to bind to membrane associated TK1 across four different cancer cell lines." (PMID 32317865, 2020).
cancer (continued). "If elevated levels of TK1 are found in the sera of patients, further clinical investigation is required to determine if the elevation is a result of cancer or other cause." (PMID 33292474, 2020). "Cancer mutations or deletions in the C-terminal region abolish cell cycle-specific degradation and allow TK1 to be expressed even in G0." (PMID 33292474, 2020). "TK1 has been investigated as a diagnostic and prognostic biomarker for several types of cancer, including LUAD." (PMID 32925947, 2020). "A previous study, showed that serum TK1 is a potential biomarker for early cancer detection in people at risk for developing, or those who already have, precancerous growth." (PMID 31589613, 2019). "Thymidine kinase 1 (TK1) is overexpressed and associated with poor prognosis in a number of different cancers." (PMID 31589613, 2019). "Because of this critical association to proliferation and the cell cycle, TK1 has been established as a proliferation biomarker in many cancers, including lung, breast, and colorectal." (PMID 30214377, 2018). "TK1 levels are elevated in cells dysregulated in several pathways commonly associated with cancer, including the E2F-pRb pathway." (PMID 29018771, 2017). "Loss of Fhit protein activity causes replication stress through reduced Thymidine Kinase 1 expression, increased DNA breaks, and global genome instability in normal and cancer cells." (PMID 25401976, 2015). "TK1 has been studied extensively, primarily as a diagnostic biomarker for a variety of cancer types and it is associated with proliferating cells and is primarily elevated during S phase." (PMID 23717685, 2013). "Nuclear TK1 expression is associated with aggressive features of cancer, as demonstrated by its prognostic significance in terms of 5-year survival rates." (PMID 23693054, 2013). "Nuclear TK1 expression in patients with CIN grade I to III can provide reliable proliferation rate information that is useful for early risk assessment of cancer progression and treatment choices for individuals." (PMID 23693054, 2013). "High levels of TK1 enzyme activity in serum are also associated with cancer grade and stage." (PMID 39006942, 2024). "A study containing 56,178 people revealed that serum TK1 (sTK1) might be a potential marker for predict persons in the risk of pre-cancer or already trapped in cancer." (PMID 38480789, 2024). "Additionally, serum levels of TK1 have been shown to be associated with cancer staging, with higher levels of TK1 indicating a more severe prognosis." (PMID 38761234, 2024). "Increased expression of TK1 has been shown to be associated with cancer aggressiveness." (PMID 38033034, 2023). "We analyzed the relationship between TK1 and the survival prognosis of patients with 33 types of cancer, and the results showed that high TK1 expression was associated with impaired survival in more than 10 cancers." (PMID 37767092, 2023). "Additionally, some TK1 forms seem to be able to associate to the cell membrane of cancer cells, an event that is apparently restricted to malignancy." (PMID 35239730, 2022). "TK1 is overexpressed in numerous cancers and is associated with to a poor prognosis." (PMID 36035114, 2022). "Recent studies indicate that in addition to its role as a biomarker of cancer cell proliferation, TK1 is also involved in cancer cell invasion and progression, although the underlying mechanism remains unknown." (PMID 35127491, 2021). "Consequently, serum TK1 has been used as a diagnostic and prognostic cancer biomarker, mainly in human medicine." (PMID 34906077, 2021). "Therefore, serum TK1 has been used in health screening to detect premalignant diseases and as a diagnostic and prognostic biomarker for cancer in human medicine." (PMID 34906077, 2021). "It has been determined that increased tissue expression of TK1 is linked to aggressive cancer types and that this upregulation is an early event—as such, TK1 may be used to predict the presence of disease earlier." (PMID 33292474, 2020).
cancer (continued). "Despite its advantages as a biomarker, TK1 is perhaps best used in tandem with other markers or procedures, given that elevated levels of TK1 in the serum may be caused by inflammation or infection and not only by cancer." (PMID 33292474, 2020). "While TK1 levels have been primarily used to monitor the development of malignancy, it has been suggested that overexpression of TK1 or malignant associated forms of the enzyme could be used for the targeting of cancer." (PMID 32317865, 2020). "The experiments presented here provide early evidence that the targeting of membrane associated TK1 with monoclonal antibodies may be a feasible approach for the treatment of cancer." (PMID 32317865, 2020). "Thus, TK1 in the blood circulation may indicate the release of TK1 from sources other than cancers, nonetheless associated with OS." (PMID 36982234, 2023). "In addition, there is an intimate association between TK1 expression and cancer prognosis." (PMID 35311151, 2022). "In addition, it has been reported, that some forms of TK1 seem to be able to associate to the cell membrane of several cancer cell types, including leukemia, breast, lung and colon tumor cells possibly through protein-protein interaction or transitory membrane localization through exosomes." (PMID 35239730, 2022). "Furthermore, if membrane expression of TK1 is restricted to malignant cells, then the detection of membrane associated TK1 forms may be a hallmark linked to the development of particular cancers." (PMID 32317865, 2020). "Therefore the development of an ELISA based assay, which could determine both the active and inactive TK1 protein in sera from cancer patients should be a great advantage in in-vitro diagnostics." (PMID 27079872, 2016). "The TK1 concentration in whole cancer group (mean: 684 pg/mL) was significantly higher compared to healthy dogs (mean: 144 pg/mL)." (PMID 40351765, 2025). "Even though the TK1 concentration and cCRP alone have an AUC of 0.75 but when we combine TK1 with cCRP the AUC significantly increased to 0.89 which clearly indicate the complimenting of these two biomarkers in cancer detection." (PMID 40351765, 2025). "Earlier published studies showed that this approach of CRP and TK1 increase the specificity of cancer detection." (PMID 40351765, 2025). "To further validate the oncogenic relevance of thymidine kinase 1 (TK1), we examined its expression across different cancer types and clinical stages using multiple public databases." (PMID 40564887, 2025). "CDK1+ cancer cells and TK1+ cancer cells, which have high levels of cell cycle activity, were abundant in resistant cases." (PMID 41016944, 2025). "This has enabled us to understand the structural events that promoted the binding inhibition of PKAc and TK1, potentially ameliorating cancer and aiding in the structural design of more effective drugs for treating CRC." (PMID 40699738, 2025). "Together, these in vitro findings demonstrate that TK1 is not only overexpressed in OSCC but also functionally contributes to the migratory behavior of cancer cells." (PMID 40564887, 2025). "In cancer cells, rapid proliferation leads to abnormal TK1 activation, reducing reliance on TK2, whereas PS cells exhibit selective TK2 downregulation as part of their metabolic transition toward glycolysis and reduced mitochondrial activity." (PMID 40571767, 2025). "Analysis via the TIMER2.0 platform revealed that TK1 expression was markedly elevated in a wide range of cancer types compared to corresponding normal tissues, supporting its general association with tumorigenesis." (PMID 40564887, 2025). "TK1 is an enzyme involved in DNA synthesis and repair, and its levels are often elevated in rapidly dividing cells, such as cancer cells and has been studied as a potential biomarker for cancer diagnosis and monitoring treatment response." (PMID 40830177, 2025).
cancer (continued). "In summary, while CRP is a valuable marker for inflammation, its nonspecific nature necessitates the inclusion of additional biomarkers, such as TK1, to improve the accuracy of early cancer detection." (PMID 40351765, 2025). "For instance, YBX1 is an interactive partner of lincNMR that regulates the expression of downstream RRM2, TYMS and TK1 by binding to their promoters, governing nucleotide metabolism and cell proliferation in cancer." (PMID 38491348, 2024). "The commonly upregulated gene observed in cisplatin for both cancers was TK1, which is an indicator of DNA damage." (PMID 39061185, 2024). "While TOP50 genes negatively related to TK1 were enriched in proteoglycans in cancer, Hedgehog signaling pathway and TGF-beta signaling pathway." (PMID 38480789, 2024). "We demonstrated that the TK1 enzyme activity is higher in EVs derived from the malignant cell lines, with the highest activity from cells deriving from the most aggressive cancer, compared to the prostasomes and RWPE-1 EVs." (PMID 39006942, 2024). "Herein, we analyzed the TK1 expression level in pan-cancer and found that TK1 was upregulated in a variety of cancers including UCEC." (PMID 38480789, 2024). "These forthcoming studies hold promise to offer valuable insights and enhance our comprehension of the intricate role of TK1 in cancer biology." (PMID 39006942, 2024). "For malignant cells, consistently upregulated metabolic genes were predominantly associated with cancer hallmark pathways, including glycolysis (GAPDH, GPI and LDHA), OXPHOS (COX6B1 and ATP5MC2), and nucleotide metabolism (TK1, GUK1, NME1)." (PMID 39393173, 2024). "TK1 upregulation in neoplastic cells is an early event and has been shown to be detectable in cancer patients before clinical symptoms develop." (PMID 38033034, 2023). "TK1 is a cytosolic protein involved in nucleotide biogenesis that leaks out from cancer cells when they die." (PMID 37377898, 2023). "Here, we evaluate potential pathogenic effects of elevated TK1 expression by comparing HCC 1806 to HCC 1806 TK1-knockdown cancer cells (L133)." (PMID 38033034, 2023). "After evaluating levels of TK1 indifferent cancer types, we wanted to narrow our research to a particular cancer type." (PMID 38033034, 2023). "To identify the potential cancer-promoting pathways that are influenced by TK1 we compared HCC 1806 wild-type and HCC 1806 TK1-knockdown (L133) cells." (PMID 38033034, 2023). "Evidence has shown that serum TK1 is a reliable biomarker for detecting malignant tumors in cancer screening." (PMID 36831773, 2023). "TK1 expression is barely detectable in normal serum but is variably high in malignant tumors, depending on the type, stage, growth rate, and treatment of malignant tumors." (PMID 37767092, 2023). "Narrowing down the list to these factors enabled us to identify proteins through qRT-PCR that potentially play a strong role in cancer progression, cell cycle checkpoint, cell proliferation, TK1 regulation, and DNA damage." (PMID 38033034, 2023). "Special attention was given to thymidine derivatives due to their ability to target the enzyme thymidine kinase 1 (TK1), which is overexpressed in different cancers." (PMID 37894311, 2023). "We first confirmed the upregulation of cytosolic TK1 in several different cancer types using RNA-seq data from The Cancer Genome Atlas (TCGA)." (PMID 38033034, 2023). "Further studies need to be performed to clarify the extent and mechanisms of this difference in the specific activities of serum TK1 in healthy persons and those with cancer diseases." (PMID 36900385, 2023). "Recent findings suggest that intracellular TK1 is correlated with cancer cell invasion and progression, along with its signature role in cancer cell proliferation." (PMID 36035114, 2022). "TK1 expression is upregulated during the early stages of cancer development and elevated levels are detected in the serum of cancer patients making it an ideal biomarker." (PMID 35203388, 2022).